CCDC73 (coiled-coil domain containing 73)
Synonyms: NY-SAR-79
Tractability: No criterion of Open Targets' tractability assessment is met for any kind of drug.
Gene: Protein-coding gene on chromosome 11 (32,602,721 to 32,794,662, reverse strand). Ensembl gene ENSG00000186714.
Genetic constraint (gnomAD): Loss-of-function variants: 52 observed, 59.38 expected, observed/expected ratio (o/e) 0.88, 90% interval 0.7 to 1.1. The upper end of that interval is the gene's LOEUF score, 1.1, which puts it in group 4 of 6, group 1 being the genes least tolerant of losing a copy. Missense variants: 761 observed, 896.61 expected, observed/expected ratio (o/e) 0.85, 90% interval 0.8 to 0.9. Synonymous variants: 294 observed, 306.2 expected, observed/expected ratio (o/e) 0.96, 90% interval 0.87 to 1.06.
Homologues: Orthologues: chimpanzee CCDC73 (99% identical), macaque CCDC73 (93% identical), dog CCDC73 (76% identical), pig CCDC73 (69% identical), rat Ccdc73 (61% identical), mouse Ccdc73 (61% identical), rabbit CCDC73 (52% identical), zebrafish ccdc73 (14% identical).
Diseases named in the same sentence as CCDC73 in open-access papers:
CCDC73 is named in the same sentence as 5 diseases in open-access papers, as found by Europe PMC text mining. Sharing a sentence is not in itself a finding about the gene and the disease. The quoted sentences say what the papers report.
endometrial cancer (1 paper, 2020). Primary or metastatic malignant neoplasm involving the endometrium (mucous membrane that lines the endometrial cavity). "CCDC73 is associated with ovarian cancer, hepatocellular carcinoma, and endometrial cancer." (PMID 32596394, 2020).
lung carcinoma (1 paper, 2023). "A previous study has shown that lung cancer patients with a high transcription level of the CCDC73 gene tend to have a good prognosis." (PMID 37298272, 2023).
cancer (1 paper, 2020). A tumor composed of atypical neoplastic, often pleomorphic cells that invade other tissues. "Besides, 11 genes in the signature, such as coiled-coil domain containing 73 (CCDC73) and protein kinase, DNA-activated, and catalytic subunit (PRKDC), are proved to be prognosis marker genes or strongly associated with prognosis and progress of other types of cancer in published literature already." (PMID 32596394, 2020).
CCDC73 also shares sentences with these, for which no sentence is quoted: hepatocellular carcinoma (1 paper); ovarian carcinoma (1).